ENSG00000295581 (novel transcript)
Gene: Long non-coding RNA gene on chromosome 11 (4,203,295 to 4,217,046, reverse strand). Ensembl gene ENSG00000295581.
Gene Ontology:
Biological process: SRP-dependent cotranslational protein targeting to membrane, signal sequence recognition
Cellular component: signal recognition particle, endoplasmic reticulum targeting